PDCD4 (programmed cell death 4)
Diseases named in the same sentence as PDCD4 in open-access papers (continued):
Sharing a sentence is not in itself a finding about the gene and the disease.
myocardial ischemia (4 papers, 2018 to 2024). A disorder of cardiac function caused by insufficient blood flow to the muscle tissue of the heart. "PDCD4 has been suggested to underlie cardiomyocyte apoptosis induced by myocardial ischemia injury and progressive ventricular remodeling." (PMID 38503934, 2024). "Furthermore, we evaluated whether PDCD4 and BID involving mitochondrial fission engage in the regulation of apoptosis in cardiomyocytes post MI to learn more about the pathophysiological significance of PDCD4 in myocardial ischemia injury." (PMID 38503934, 2024).
papilloma (4 papers, 2009 to 2016). A benign epithelial neoplasm that projects above the surrounding epithelial surface and consists of villous or arborescent outgrowths of fibrovascular stroma. "In addition, Pdcd4-deficient mice were shown to be more susceptible to the two stage skin carcinogenesis model, whereas transgenic overexpression of Pdcd4 decreased papilloma incidence and multiplicity." (PMID 23056346, 2012). "Pdcd4 transgenic mice showed lower tumour incidence and papilloma-to-carcinoma conversion frequency compared with wild-type mice." (PMID 19728867, 2009). "Then, experiments from both the PDCD4 transgene and knockout mice indicated that PDCD4 could inhibit cutaneous tumor incidence and papilloma-to-carcinoma conversion-frequency induced by TPA (12-O-tetradecanoylphorbol-13-acetate)." (PMID 26703592, 2015).
pulmonary arterial hypertension (4 papers, 2022 to 2025). Pulmonary arterial hypertension (PAH) is a group of diseases characterized by mean pulmonary artery pressure >20 mmHg and elevated pulmonary arterial resistance leading to right heart failure. "In the myocardium and pulmonary aorta of rats with pulmonary arterial hypertension, the expression of miR-200a-3p is upregulated, inhibiting the expression of IGF1R and PDCD4." (PMID 40997050, 2025).
rectal cancer (4 papers, 2016 to 2025). A primary or metastatic malignant neoplasm that affects the rectum. "The inflammatory secretome of macrophages has been found to suppress PDCD4 expression in cancer cells such as RKO rectal carcinoma cells, indicating that PDCD4 expression is regulated by inflammation." (PMID 35847932, 2022). "Programmed cell death 4 (PDCD4) may play a role in radiotherapy-induced AKI in rectal cancer by upregulating FGR expression, activating the NF-κB signaling pathway, and triggering an oxidative stress response." (PMID 40911105, 2025). "Similarly, our results showed that miR-21 works through the target genes PTEN and PDCD4, which is consistent with the results of rectal cancer research." (PMID 34378676, 2021).
triple-negative breast carcinoma (4 papers, 2015 to 2022). An invasive breast carcinoma which is negative for expression of estrogen receptor (ER), progesterone receptor (PR), and human epidermal growth factor receptor 2 (HER2). "High levels of the oncogenic miRNA (oncomiR) guide strand called miR-17-5p is overexpressed in triple negative breast cancer (TNBC) and can inhibit ribosomal translation of tumor suppressor gene mRNAs, such as programmed cell death 4 (PDCD4) or phosphatase and tensin homolog (PTEN)." (PMID 26629823, 2015).
Alzheimer disease (3 papers, 2020 to 2023). A progressive, neurodegenerative disease characterized by loss of function and death of nerve cells in several areas of the brain leading to loss of cognitive function such as memory and language. "Seven out of 18 genes are associated with neurological diseases: Alzheimer’s disease (CPT1A, SUFU, ZSWIM8, PDCD4), schizophrenia (HTT, NBEAL2) and Parkinson disease (PRDM13)." (PMID 32599769, 2020). "Besides, in Alzheimer’s disease, miR-212 modulates PDCD4 through PI3K/AKT signaling pathway to allay Aβ25-35-induced neurotoxicity." (PMID 34180760, 2021). "Interestingly, there were seven genes associated with neurological disorders, including Alzheimer’s disease (CPT1A, SUFU, ZSWIM8, PDCD4), schizophrenia (HTT, NBEAL2) and Parkinson’s disease (PRDM13)." (PMID 32599769, 2020).
cholesteatoma (3 papers, 2022 to 2024). A pathologic process characterized by the proliferation of keratinizing squamous epithelium resulting in the accumulation of keratin and cells in the middle ear and/or mastoid. "In effect, miR-21 upregulation results in the inhibited translation of PTEN and PDCD4 (programmed cell death 4), which are important regulators of cell division, in effect causing constant keratinocyte proliferation and cholesteatoma invasion." (PMID 37047725, 2023). "As a result, miR-let-7a upregulation may increase the expression of the miR-21 target genes PTEN and PDCD4 as part of a mechanism for inhibiting keratinocyte proliferation and cholesteatoma growth." (PMID 37047725, 2023). "Upregulation of miR-21 by targeting PTEN and PDCD4 could regulate apoptosis, proliferation, invasion, and migration of Cholesteatoma." (PMID 35402235, 2022). "They found out that the upregulation of miR-21 expression in cholesteatoma was negatively correlated with the expression of PTEN and PDCD4." (PMID 38890701, 2024).
colorectal tumor (3 papers, 2013 to 2020). "Taken together, SRSF3 represses PDCD4 AS-1 mRNA at the translational level, and PDCD4 AS-2 mRNA at the alternative splicing and mRNA export levels, finally promoting the proliferation and migration of colorectal tumors." (PMID 32284746, 2020). "Recent studies have shown a progressive reduction in PDCD4 expression from normal mucosa, to polyp, to colorectal tumour." (PMID 25310697, 2014). "Although we only used a small patient cohort in this study, nevertheless we saw a clear correlation between downregulation of Pdcd4 and miR-34a and enhanced expression of miR-21, CD24 and Src in the resected colorectal tumor samples compared to normal tissue." (PMID 23533633, 2013).
injury (3 papers, 2016 to 2024). Damage inflicted on the body as the direct or indirect result of an external force, with or without disruption of structural continuity. "Our previous study also indicates that xenon preconditioning inhibited PDCD4 expression and NF-κB activity to protect LPS-induced kidney injury by increasing miR-21 levels." (PMID 30013485, 2018).
myocarditis (3 papers, 2016 to 2022). Myocarditis is a condition that is characterized by inflammation of the heart muscle (myocardium). "miR-21 can alleviate CVB3-induced myocarditis by protecting myocardial apoptosis by repressing programmed cell death 4 (PDCD4) expression." (PMID 36017100, 2022). "MiR-21, which targets Programmed Cell Death 4 (PDCD4), is suppressed in CVB3-induced myocarditis and serves as an anti-apoptotic molecule." (PMID 26751468, 2016). "Programmed cell death 4 (PDCD4)-mediated apoptosis is an important component that propagates CVB3-induced myocarditis, and CVB3 reduced the amount of miR-21 that could directly inhibit PDCD4 in a mouse model, leading to continuous apoptosis and worsened myocarditis." (PMID 33809362, 2021).
ovarian tumor (3 papers, 2009 to 2019). "MiR-21 inhibits the expression of programmed cell death 4 (PDCD4), which is directly related to poor prognosis of ovarian tumor patients." (PMID 31639019, 2019). "In conclusion, both localization and expression level of Pdcd4 might be the potential indicators of ovarian tumour progression." (PMID 19728867, 2009). "However, the regulatory mechanisms of Pdcd4 in ovarian tumour progression remained to be further investigated." (PMID 19728867, 2009).
pancreatic ductal adenocarcinoma (3 papers, 2018 to 2025). An infiltrating adenocarcinoma that arises from the epithelial cells of the pancreas. "Only one previous study has evaluated PDCD4 immunohistochemical expression patterns, nuclear vs. cytoplasmic, in pancreatic ductal adenocarcinoma prognosis, but this study was based on a small patient cohort, and PDCD4 subcellular expression levels were measured using semiquantitative methods." (PMID 33801444, 2021).
renal fibrosis (3 papers, 2019 to 2022). A final common manifestation of a wide variety of chronic kidney diseases characterized by glomerulosclerosis and tubulointerstitial fibrosis. "A recent study demonstrated that a feedback loop between miR-21 and programmed cell death protein 4 (PDCD4) and activated protein (AP-1) drives progression in a mouse model of renal fibrosis." (PMID 31474862, 2019).
retinal ischemia (3 papers, 2021 to 2024). A ischemic disease that involves the retina. "In retinal ischemia-reperfusion, lncRNA H19/miR-21/PDCD4 axis can directly adjust microglia relaxation and neuron damage caused by I/R." (PMID 34180760, 2021). "In a model of retinal ischemia/reperfusion injury, TNF-α stimulated extracellular vesicles miR-21-5p secreted by gingival mesenchymal stem cells (GMSCs) was found to convert microglia from the Iba-1+/CD86+ state to the Iba-1+/Arg-1+ state by combining with programmed cell death 4 (PDCD4)." (PMID 37693651, 2023).
retinoblastoma (3 papers, 2017 to 2024). A malignant tumor that originates in the nuclear layer of the retina. "In retinoblastoma, circMKLN1 could play a tumor suppressive role, and the mechanism may be through sponge adsorption of miR-425-5p, which in turn promotes PDCD4 and inhibits proliferation, migration and invasion of tumor cells." (PMID 38460002, 2024).
squamous cell carcinoma (3 papers, 2014 to 2019). A carcinoma arising from squamous epithelial cells. "These 3′-UTR mutants were then cloned into the dual-luciferase reporter system psiCHECK-2 and transfected into UMSCC22B hypopharyngeal squamous cell carcinoma cells to ascertain the contribution of each individual site to PDCD4 regulation." (PMID 31235478, 2019). "Like CSL, PDCD4 is down-regulated in stromal fibroblasts of premalignant skin actinic keratosis (AKs) lesions and squamous cell carcinoma (SCC)." (PMID 27542230, 2016).
Anxiety (2 papers, 2021 to 2024). Intense feelings of nervousness, tension, or panic often arise in response to interpersonal stresses. "We next examined the effect of Pdcd4 knockdown on CRS-induced anxiety-like behaviors." (PMID 32203159, 2021). "Further, we also investigated the effect of Pdcd4 KO on CRS-induced anxiety-like behaviors." (PMID 32203159, 2021). "Unexpected, knockdown of Pdcd4 after CRS could not rescue the anxiety-like behavior caused by CRS in mice, that is different from the effect of Pdcd4 knockdown on depression-like behavior." (PMID 32203159, 2021). "Interestingly, the LPS-induced increase in anxiety-like behaviors in control mice was not reversed by microglial Pdcd4 knockout." (PMID 38822367, 2024).
asthma (2 papers, 2013 to 2017). "Programmed cell death 4 (Pdcd4), initially known as a tumor-suppressor gene, has also been associated with severe asthma in children." (PMID 28106744, 2017). "Focusing our analysis in childhood asthma, we conducted fine mapping of the PDCD4 region revealing two further SNP associations with severe asthma, rs34104444:G>A and rs1322997:C>A (P = 0.004 and P = 0.002, respectively)." (PMID 23606399, 2013). "In conclusion, this study combining a genetic analysis in well-defined population of severe asthmatics and controls, incorporating functional approaches reports that PDCD4 locus is associated with severe asthma and IgE levels, whereas SNP rs6585018:G>A exerts a regulatory effect on PDCD4 expression." (PMID 23606399, 2013). "The results from this study have shown that the putative promoter-located PDCD4 SNP rs6585018:G>A is associated with severe asthma in children and that it could influence the transcription of the PDCD4 gene in an allele-dependent manner." (PMID 23606399, 2013). "Nevertheless, PDCD4 SNPs associations with the asthmatic status seen for the UK group and IgE levels seen for both children groups from the UK and Germany indicate that PDCD4 is a locus of interest for the development of early onset severe asthma." (PMID 23606399, 2013). "In an OVA-induced rat asthma model, Pdcd4 was found up-regulated in rat lung tissue and gene silencing of Pdcd4 by siRNA reduced inflammatory cell infiltration and ameliorated airway remodeling." (PMID 28106744, 2017). "Allele G associated with severe asthma and higher total IgE levels leads to less MYB binding and therefore lower PDCD4 expression as it is evident by the functional analyses." (PMID 23606399, 2013). "Our association between a variant MYB binding site in PDCD4 and the severest form of childhood asthma therefore suggests that PDCD4 is a novel molecule of importance to asthmatic inflammatory responses." (PMID 23606399, 2013). "Our study focused on PDCD4 SNP rs6585018:G>A as the one significantly associated with severe asthma and also predicted to have a functional role; however, due to the small size of our severe asthmatic children group, we cannot fully disregard the rest of the GWAS hits as nonassociated with asthma." (PMID 23606399, 2013). "We therefore propose that the PDCD4 protein and MYB-dependent regulation would be worthwhile for further investigation of its role in asthma-related mechanisms." (PMID 23606399, 2013).
atrial fibrillation (2 papers, 2025). A disorder characterized by an electrocardiographic finding of a supraventricular arrhythmia characterized by the replacement of consistent P waves by rapid oscillations or fibrillatory waves that vary in size, shape and timing and are accompanied by an irregular ventricular response. "Taken together, these findings shed light on the multifaceted biochemical and molecular pathways associated with PDCD4 and underscore its potential role in the development of atrial fibrillation." (PMID 40766329, 2025). "Therefore, investigating the pan-cancer expression, prognostic value, and immunological relevance of PDCD4 may provide broader insight into its therapeutic potential beyond atrial fibrillation." (PMID 40766329, 2025).
bacterial pneumonia (2 papers, 2013 to 2018). Acute infection of the lung parenchyma caused by bacteria (e.g., Streptococcus pneumoniae, Haemophilus influenzae, Chlamydia pneumoniae, Mycoplasma pneumoniae, and Legionella pneumophila). "Therefore the pro-inflammatory contribution of PDCD4 to host signaling during bacterial pneumonia could significantly contribute to lung pathology." (PMID 24098127, 2013). "Cohen and Prince showed that during bacterial pneumonia type III IFNλ promotes inflammation by inhibiting miR-21, upregulating PDCD4, and consequently diminishing IL-10 production." (PMID 29942317, 2018).
cancers of stomach (2 papers, 2016). "Finally, we revealed that miR-93 promoted the development of gastric tumor growth in xenograft mice by negatively regulating PDCD4." (PMID 27021515, 2016).
cervical (2 papers, 2015 to 2022). "Furthermore, microRNA‐21 affects other direct target molecules including PDCD-4, TPM-1, FASL, and BTG-2 in order to stimulate its cervical carcinogenesis effect." (PMID 35895593, 2022).
childhood asthma (2 papers, 2013 to 2023). "Our study identified a SNP, rs6585018:G>A, located within the predicted promoter region of the PDCD4 gene on chromosome 10q24 to be significantly associated with childhood asthma (P = 0.001)." (PMID 23606399, 2013). "Three SNPs in the PDCD4 gene (rs6585018:G>A, rs1322997:C>A, and rs34104444:G>A) were significantly associated with severe childhood asthma (P values: 0.003, 0.002, 0.004) and total immunoglobulin E (IgE) levels (P values: 0.034, 0.041, 0.052)." (PMID 23606399, 2013). "Recently, a genome-wide association study on severe asthmatics in a European cohort found significant associations between SNPs in the programmed cell death 4 (PDCD4) gene and severe childhood asthma and total IgE levels." (PMID 37426425, 2023).
Clear Cell Renal Cell Carcinoma (2 papers, 2021 to 2025). "We developed and validated a 100-gene expression signature based on PDCD4 co-expression patterns that serves as a robust prognostic biomarker in clear cell renal cell carcinoma." (PMID 41614853, 2025). "In this comprehensive study, we developed and validated a novel PDCD4-based gene expression signature for predicting overall survival in clear cell renal cell carcinoma." (PMID 41614853, 2025).
coronary artery disease (2 papers, 2024). "In another study with single-, dual-, and multivessel occluded coronary artery disease (CAD) patients, the expression of plasma miR-21 was evidently and progressively higher, while the programmed cell death protein 4 (PDCD4) level was significantly and steadily lower compared to healthy controls." (PMID 39457065, 2024).
coronary atherosclerosis (2 papers, 2020 to 2022). Atherosclerosis of the coronary vasculature. "It has been established that PDCD4 is crucial in regulating oxidized low-density lipoprotein (ox-LDL) metabolism, foam cell formation, coronary atherosclerosis, stress, and ischemia/reperfusion-induced cellular injuries." (PMID 35814945, 2022).
cutaneous melanoma (2 papers, 2021 to 2022). A primary melanoma arising from atypical melanocytes in the skin. "Lastly, we treated three cutaneous melanoma cell lines with Nutlin-3 for 24 h and investigated the mRNA expression of RFX7, RFX5, PNRC1, PDCD4 and CDKN1A as positive control." (PMID 36139642, 2022). "This may explain why the The Cancer Genome Atlas skin melanoma fails to show a correlation between PDCD4 and PLEKHA5 mRNA levels." (PMID 33801444, 2021).
cyst (2 papers, 2012 to 2023). A sac-like closed membranous structure that may be empty or contain fluid or amorphous material. "The potential mechanism by which miR-21 exacerbates cyst growth may involve direct inhibition of the pro-apoptotic tumor suppressor gene programmed cell death 4 (PDCD4)." (PMID 37680850, 2023).
glaucoma (2 papers, 2021 to 2023). Increased pressure in the eyeball due to obstruction of the outflow of aqueous humor. "It is found that miR-93-5p decreases retinal neuron apoptosis through suppressing PDCD4 in acute ocular hypertension model, which indicates miR-93-5p as a therapeutic target of glaucoma." (PMID 37308277, 2023). "Our results showing miR-21 protection against retinal disorders only join with another study demonstrating that the miR-21/Pdcd4 axis regulates MSC-induced neuroprotection in glaucoma, indicating target-specific regulatory effects based on Pdcd4 inhibition." (PMID 33082517, 2021).
Hepatic fibrosis (2 papers, 2019 to 2023). The presence of excessive fibrous connective tissue in the liver. "In conclusion, PDCD4 knockdown induced premature senescence in human HSCs and changed their phenotype to a less-fibrogenic one, suggesting that PDCD4 may be a target for limiting liver fibrosis." (PMID 36522523, 2023). "Therefore, PDCD4 may help limit the development of liver fibrosis." (PMID 36522523, 2023).
hyperlipidemia (2 papers, 2016 to 2021). "Loss of PDCD4 in a murine model of hyperlipidemia was associated with decreased CD8+ T cells and increased regulatory T cells." (PMID 33801444, 2021).
Insulin resistance (2 papers, 2024 to 2025). Increased resistance towards insulin, that is, diminished effectiveness of insulin in reducing blood glucose levels. "Another group also reported that PDCD4 deficiency ameliorated left ventricular remodeling and insulin resistance in a rat model of type 2 diabetic cardiomyopathy." (PMID 41439995, 2025). "Therefore, PDCD4 may be associated with the induction of inflammatory diseases and insulin resistance and BCAA intake may exacerbate the inflammatory diseases via the upregulation of PDCD4." (PMID 41439995, 2025).